TNF (tumor necrosis factor)
Diseases named in the same sentence as TNF in open-access papers (continued):
Sharing a sentence is not in itself a finding about the gene and the disease.
melanoma (continued). "As the poor-switching melanoma cell lines Ma-Mel-15 and Ma-Mel-102 hardly induced endogenous c-Jun in response to TNF-α, we stably overexpressed green fluorescent protein (GFP)-tagged c-Jun (Jun–GFP)." (PMID 26530832, 2015). "In this paper, we identified CD271 as a new mechanism of acquired resistance of melanoma cells to BRAFi that involves tumor necrosis factor-alpha (TNFα)/NF-κB pathway activation and sustained CD271 expression." (PMID 27462428, 2015). "Stimulation of melanoma cells and monocytes by lipopolysaccharide resulted in cytoplasmic translocation of hnRNPD from nucleus and reduced levels of IL-6, IL-10 and TNF-α following activation of MKP-1 (MAPK phosphatase-1)." (PMID 26318153, 2015). "Subsequently, we analysed the transcriptional changes on TNF-α treatment in strong and poor switching melanoma cell lines in time-course experiments." (PMID 26530832, 2015). "Another study performed on melanoma patients in stage II and III reported the combination of serum TNF-alpha, soluble IL-2 receptor and beta-2 microglobulin to be strong predictive markers of relapse in melanoma before treatment." (PMID 32309563, 2015). "We found that TNF-α responsiveness was highly heterogeneous, but MITFlow melanoma cell lines had significantly higher inflammatory pathway activity both in the presence and absence of TNF-α." (PMID 26530832, 2015). "Taken together, these results demonstrated that vemurafenib controls CD271 in a TNFα/NF-κB-dependent manner in A375 melanoma cells." (PMID 27462428, 2015). "In the B16 mouse melanoma tumor model, silencing of A20 enhances the CpG-triggered induction of NFκB activity followed by elevated expression of IL-6, TNF-α and IL-12." (PMID 26327508, 2015). "One of the main mechanisms that likely accounts for the TNF-dependent immunosuppression in our experimental mouse melanoma model is the capacity of TNF to trigger cell death of activated CD8+ T cells." (PMID 26622939, 2015). "We have recently provided evidence that host TNF signaling impairs CD8+ T cell-dependent immune response against melanoma." (PMID 26622939, 2015). "Clinical studies with compounds targeting the death receptor family were initiated several years ago in tumors other than melanoma, with the use of recombinant human (rh)TNF-α." (PMID 24920406, 2014). "Consistently, LY294002 suppressed the TNF-induced upregulation of GFPhighABCB5high melanoma SCs, strongly supporting AKT involvement in the TNF-mediated regulation of melanoma SC fate determination and functionality." (PMID 25223735, 2014). "Experiments with human malignant melanoma tissues and cell lines have shown that proinflammatory cytokines, such as IL-1α/β and TNF-α, produced by melanoma cells activate p38 kinase to promote the IFN-α/β-independent pathway of IFNAR1 degradation." (PMID 24516470, 2014). "Melanoma metastases from 37 patients were stained for TNF-α: 16 metastases were from untreated patients and 21 were from patients treated with IFN-α." (PMID 24516470, 2014). "The present study shows that, inflammatory macrophages co-cultivated with B16 murine melanoma cells express enhanced VEGF-C mRNA which was found to be associated with an autocrine loop of activity between macrophage IL-1β and TNF-α and their receptors." (PMID 25120672, 2014). "For example, TNF was shown to induce the reversible dedifferentiation of melanoma cells and an increased melanocyte number while inhibiting their differentiation-related pigmentation." (PMID 25223735, 2014). "Altogether, these data infer that TNF expands the pool of GFPhigh ABCB5high CD271high sphere-initiating melanoma SCs." (PMID 25223735, 2014). "The BMDCs groups treated with TNFα/MAGE-AX or GK-1 had a survival of at least 10% at day 40, while 40% of the mice that received the BMDC treatment with TNFα/MAGE-AX/GK-1 achieved a 40% survival rate up to 1.5 years after being inoculated with melanoma." (PMID 25759825, 2014).
melanoma (continued). "Of note, TNF-α displays potent anti-tumorigenic properties and thus used in the treatment of metastatic melanomas, primary or metastatic unresectable liver tumors and soft tissue sarcomas." (PMID 25208737, 2014). "To determine functional consequences of the TNF-instigated changes leading to the increase in GFPhigh cells with the melanoma SC phenotype, we performed functional tests using tumor-like sphere cultures." (PMID 25223735, 2014). "Moreover, previous studies demonstrated that the combination of tumor immunotherapy with IL-12 and TNF-α may be more effective to mouse melanoma, and heparan sulfate causes the release of TNF-α and IL-12, and induces cytotoxic capability in peritoneal macrophages." (PMID 24992906, 2014). "Using an inducible H2B-GFP tracing system, we demonstrated for the first time that TNF increases the sub-population of quiescent or slow-cycling melanoma stem-like cells." (PMID 25223735, 2014). "Results of competition with TNF-α receptors in surface plasmon resonance and melanoma cells expressing both TNF receptors make the peptide a candidate compound for the development of a novel anti-TNF-α drug." (PMID 24896264, 2014). "TNF-suppressed differentiation, which was accompanied by an increase in GFPhighABCB5high sphere-initiating melanoma SCs, strongly suggests that TNF blocks the commitment of these cells to differentiation, favoring their symmetric over asymmetric self-renewal." (PMID 25223735, 2014). "Polyclonal γδTc TIL lines kill melanoma cell lines, and secrete tumor necrosis factor alpha (TNFα) and IFN-γ." (PMID 25477885, 2014). "We therefore generated A375 melanoma cell lines stably transduced with a luciferase-based reporter to the TNFα pathway." (PMID 24358901, 2013). "Isolated limb perfusion (ILP) with recombinant human tumor necrosis factor-α (rhTNF-α, or tasonermin) and melphalan is a highly effective treatment for soft tissue sarcoma and in-transit metastases of malignant melanoma of the extremities." (PMID 22948772, 2013). "In support of this finding, exogenous TNFα was found to inhibit apoptosis in melanoma cells with abrogated B-Raf signaling through the activation of the NFκB pathway." (PMID 23965971, 2013). "Inhibition of endogenous PGE2 production by a COX-2 inhibitor, COX-2 siRNA or an NFκB inhibitor suppressed MCP-1 expression, whereas treatment with TNF-α (to stimulate endogenous PGE2 production) or exogenous PGE2 enhanced MCP-1 expression in melanoma cells." (PMID 23420676, 2013). "As such, it will be crucial to delineate the pathways involved in mediating TNFα secretion from melanoma cells to selectively enhance or inhibit its levels." (PMID 23965971, 2013). "Our studies and earlier investigations by Sumimoto suggest that suppression of IL-12 and TNF-α production by DCs in the tumor microenvironment of a BRAFV600 mutant melanoma is mediated at least partially by constitutive activation of the MAPK pathway." (PMID 24194739, 2013). "We found that IL-12 and TNF-α production by DCs was inhibited when DCs were exposed to melanoma cells treated with vehicle control." (PMID 24194739, 2013). "As shown, each of the 8 melanoma cell lines stimulated both clones, with variable intensities in TNF responses while normal melanocytes were poorly stimulatory." (PMID 24086473, 2013). "We tested the capacity of eight HLA-A0201+ melanoma cell lines and two HLA-A0201+ melanocyte cell lines to stimulate TNFα production by the two clones." (PMID 24086473, 2013). "We demonstrate that CTLA-4 engagement with Ipilimumab triggers innate immune cells to ADCC of CTLA-4+ melanoma cells and Tumor Necrosis Factor (TNF)-α production." (PMID 23634660, 2013). "Constitutive upregulation of the MAPK pathway in BRAFV600 mutant melanoma appears to directly impact DC function as evident by partial restoration of IL-12 and TNF-α secretion upon treatment of melanoma cells with MEK or BRAF inhibition." (PMID 24194739, 2013).
melanoma (continued). "It was used as an anti-vascular agent in melanoma cells where induction of TNFα in the tumor endothelium led to a breakdown of tumor vasculature and inhibition of tumor growth in mice." (PMID 23965971, 2013). "IL-12 and TNF-α production by DCs exposed to supernatant from the BRAF mutant A375 melanoma cell line prior to maturation by LPS was suppressed." (PMID 24194739, 2013). "A report published few years ago demonstrated that melanoma cells cultured in presence of IFN-γ or TNF-α secreted KC." (PMID 24377047, 2013). "Forced expression of ATF2 increased UVC-induced cell death in melanoma cells while the addition of exogenous TNFα restored cell survival." (PMID 23965971, 2013). "Thirdly, pre-treatment with a COX-2 inhibitor clearly abrogated TNF-α-induced MCP-1 upregulation in melanoma cells." (PMID 23420676, 2013). "Future studies should probe the role, if any, of TNFα/NFκB in melanoma apoptosis and the cross-talk between Wnt/β-catenin and TNFα/NFκB signaling in cell lines, such as HeLa, that respond to TNFα by apoptosis." (PMID 24358901, 2013). "Optimization of chemoradiotherapy and antisense therapy targeting bcl-2 simplifies the treatment that eliminated metastatic B16 melanoma from the mouse liver, since avoids the need of TNF-α, and IFN-γ administration (and their side effects)." (PMID 22233801, 2012). "Tumor necrosis factor-α (TNF-α) also inhibits melanin synthesis by human primary melanoma, but it appears that ZAG inhibits melanin production via a TNF-independent mechanism." (PMID 22778983, 2012). "In conclusion, these studies reveal that ex vivo treatment with Cl-IB-MECA improves CD8+ T cell adoptive immunotherapy for melanoma in a TNF-α-dependent manner." (PMID 23028986, 2012). "TNF-α levels in melanoma tissue of mice adoptively transferred with Cl-IB-MECA-treated CD8+ T cells or mice injected once with Cl-IB-MECA were significantly increased compared with control groups." (PMID 23028986, 2012). "More importantly, VEGF --which is released to the BM microenvironment by both LPS-induced BMSCs and TNFα-stimulated melanoma cells -- was involved in melanoma-stimulating activities of BMSCs." (PMID 21867538, 2011). "These pathways are also involved in proinflammatory cytokine release like TNF-α which was shown to be involved in melanoma progression via the inhibition of apoptosis." (PMID 21961050, 2011). "Imaging studies focusing on migrating ‘fronts’ of cells revealed that melanoma cells responded with a significant increase in migration distance when stimulated with TNF-α during an in vitro scratch migration assay." (PMID 24212647, 2011). "Hypophosphorylated or transcriptionally inactive forms of ATF2 reduce TNF-α expression, resulting in sensitization of melanoma to treatment via increased apoptosis." (PMID 21429205, 2011). "Harmine significantly inhibited the production of pro-inflammatory cytokines, namely TNF-α, IL-1β, IL-6 and GM-CSF by B16F-10 melanoma cell in culture." (PMID 21429205, 2011). "More encouraging is the current clinical use of combination TNF-α with chemotherapeutic agents in the setting of hyperthermic isolated limb perfusion in limb-threatening soft tissue sarcomas and in-transit melanoma." (PMID 22036896, 2011). "In human melanoma cells, tumor necrosis factor-α (TNF-α) has been reported to upregulate integrin expression, cell attachment, and invasion of cells through fibronectin." (PMID 24212647, 2011). "The capacity to induce TNF-α production has also been shown for other exosomes such as melanoma derived exosomes." (PMID 21799736, 2011). "TNF-α and IL-2 in murine models with leukemia, mastocytoma, melanoma, lymphoma and sarcoma cell lines also demonstrate combinatorial effects and systemic immunological memory." (PMID 22036896, 2011).
melanoma (continued). "Consistent with the strong melanoma cell adhesion-stimulating activity detected in the conditioned media from LPS-treated BMSCs, TNFα and VEGF significantly (P < 0.01) increased in the supernatant of LPS-activated BMSCs as compared to untreated BMSCs." (PMID 21867538, 2011). "ITPV successfully controlled melanoma progression in vivo by an induction of Th1 type cytokines, including TNF-α and IFN-γ in both the skin and the systemic circulation." (PMID 22216160, 2011). "Thereby the protumoral cytokine profile is augmented additionally by increasing levels of TNF-α, which also has been demonstrated in a murine melanoma model." (PMID 20205946, 2010). "Of the 6 patients with a malignancy <10 years prior to starting anti-TNF therapy who later developed an incident malignancy, 3 had a prior melanoma." (PMID 20535785, 2010). "At high doses, TNF has been used as a treatment for some malignancies, including melanoma and sarcoma." (PMID 20535785, 2010). "The tumor reactivity was evaluated by the percentages of SP CD8 and DP T cells producing TNF-α in response to autologous melanoma cells." (PMID 20052413, 2010). "Consistent with these in vitro results, the expression of transcripts coding MMP-2, MMP-9, and TNF-α is similarly inhibited in the melanoma tumors recovered from HB-19 treated RET mice." (PMID 20573279, 2010). "Nevertheless, the production of TNF is lower upon stimulation by the tumor cell lines other than melanomas." (PMID 20052413, 2010). "Of the patients with prior melanomas, 3 (18%) of 17 in the anti-TNF cohort developed an incident malignancy, compared with 0 of 10 in the DMARD cohort." (PMID 20535785, 2010). "Elevated levels of TNF α were also confirmed in the peripheral blood of patients with melanoma, renal carcinoma and pancreas carcinoma." (PMID 20640152, 2010). "Patient #3 had a melanoma 3.5 years prior to anti-TNF therapy, followed by bladder cancer 2.4 years after starting therapy." (PMID 20535785, 2010). "In response to autologous melanoma cell line, this clone is lytic and produced in decreasing order the following Th1 and Th2 cytokines: IL-13, IL-4, TNF-α, GM-CSF, IL-2, IFN-γ and IL-5." (PMID 20052413, 2010). "Taken together, these ex vivo analyses demonstrate that MIC- and to a lesser extent CI-treatment induced the activation of TNF-α-producing melanoma reactive CD8+ T cells." (PMID 20498710, 2010). "Three (18%) of the 17 patients with prior melanomas in the anti-TNF cohort developed an incident malignancy, compared with 0 of 10 in the DMARD cohort." (PMID 20535785, 2010). "TNF-α is being used clinically in combination with melphalan in limb perfusion in the management of melanoma of the extremity." (PMID 24281094, 2010). "NK cell activity against B16.F10 melanoma cells was found in all treated mice as well as in untreated mice, as illustrated by TNF-α and IFN-γ production upon co-culture." (PMID 20498710, 2010). "In our series of nodular melanomas, these markers also revealed some associations with features of aggressive tumors like increased tumor thickness and ulceration, and expression of two markers (TNF-α, Apaf-1) were further increased in melanoma metastases." (PMID 19061491, 2008). "Further, Qu Spez-educated DC stimulated CD4+T cells in a allogeneic mixed lymphocyte reaction and activated melanoma antigen Melan-A/MART-1-specific M77-80 CD8+T cells as evidenced by increased secretion of TNF-α and IFNγ." (PMID 18533025, 2008). "Expression of selected hypoxia markers HIF-1α (p = 0.002), CAIX (p < 0.0001), TNF-α (p = 0.008) and Apaf-1 (p = 0.002) was significantly stronger in melanomas than in benign nevi." (PMID 19061491, 2008). "TNF-α is an important mediator of apoptosis via the "extrinsic pathway", but there are limited data on its role in human melanoma." (PMID 19061491, 2008).
melanoma (continued). "Expression of selected hypoxia markers (HIF-1α, CAIX, TNF-α, Apaf-1) was significantly stronger in melanomas than in benign nevi, indicating possible roles in early melanoma development." (PMID 19061491, 2008). "The same conclusion was presented by McIlroy and Gregoire, who showed correlation between TNF and favorable responses in meta-analyses of ten clinical trials in melanoma patients (167 patients total)." (PMID 18205933, 2008). "Unexpectedly, D5 melanoma cells cultured with IFN-γ or TNF-α, two type 1 cytokines expressed by therapeutic T cells, secreted Keratinocyte Chemoattractant (KC), MCP-1, IP-10 and RANTES and expressed mRNA for MIG." (PMID 18001476, 2007). "This system utilized the WEHI TNF-α bioassay to detect CTL recognition of COS-7 cells co-transfected with pools of melanoma cell cDNA and appropriate HLA class I cDNA." (PMID 17291333, 2007). "We found that melanoma TAMs were also capable of osteoclast differentiation when cultured in the presence of M-CSF, TNF-α and IL-1." (PMID 16641914, 2006). "In this study, we show that the percentage of γδ T cells producing TNF-α was significantly reduced in young/adult and old melanoma patients in comparison with age-matched healthy subjects." (PMID 15686597, 2005). "In contrast, blocking TNF using the human p55-IgG fusion protein in a murine B16-BL6 melanoma model reduced the number of metastatic lung tumours temporarily over 2 weeks but not after 3 weeks, possibly due to increased immune clearance of the fusion protein." (PMID 15026813, 2004). "The current in vitro study investigated the extent to which the stimulatory action of TNF-α on melanoma invasion is explained by an action on cellular migration rather than on proteolytic degradation of the surrounding matrix." (PMID 15054471, 2004). "The present study demonstrates that melanoma cell migration is increased by TNF-α in two melanoma cell lines." (PMID 15054471, 2004). "Overall, our study shows that although metastasis is a complex multisystem process involving a large number of different molecules, in the B16F10 murine melanoma model TNF plays an important and rate-limiting role." (PMID 15026813, 2004). "The finding that TNF-α increases the migration of melanoma cells is consistent with and strongly supports an inflammatory environment promoting melanoma metastases." (PMID 15054471, 2004). "First, to confirm the role of TNF in metastases in the B16F10 melanoma model, we used an anti-TNF neutralising antibody, CV1q." (PMID 15026813, 2004). "Certainly, in humans TNF alone is able to upregulate Groα (the human equivalent of KC) in keratinocytes, fibroblasts and human melanoma cell lines." (PMID 15026813, 2004). "Preincubation of HBL and C8161 melanoma cells with TNF-α (300 U ml−1) prior to introducing a ‘scratch’ resulted in an increase in the rate of migration of both melanoma cell lines." (PMID 15054471, 2004). "In support of this, we have reported previously that human HBL melanoma cells in culture respond to TNF-α with an upregulation of α3, α4 and β1 integrin expression." (PMID 15054471, 2004). "This work extends recently published findings from our group describing TNF-α increased melanoma cell attachment, invasion through fibronectin and expression of integrins α3, α4 and β1." (PMID 15054471, 2004). "We reported recently that the inflammatory cytokine tumour necrosis factor α (TNF-α) can upregulate integrin expression, cell attachment and invasion of cells through fibronectin in a human melanoma cell line (HBL)." (PMID 15054471, 2004). "In conclusion, we report that the proinflammatory cytokine TNF-α upregulates malignant melanoma invasion and migration in vitro." (PMID 12966436, 2003). "Clinical trials of isolated limb perfusion (ILP) with recombinant human TNF-α and melphalan resulted in high complete response rates of 75–90% in patients with in-transit melanoma and unresectable sarcoma of the extremities." (PMID 12610519, 2003).